INS (insulin)
Diseases named in the same sentence as INS in open-access papers (continued):
Sharing a sentence is not in itself a finding about the gene and the disease.
Obesity (continued). "The review focused on articles studying the processes involved and associations between physical activity and male fertility through immune and cardiovascular effects, endocrine modulation, the influence on obesity and insulin metabolism, and the physical impact on the body." (PMID 40429435, 2025). "Additionally, TNF-α inhibitors have been tested to attenuate the inflammatory burden in obesity and improve insulin sensitivity and prevent progression of metabolic diseases." (PMID 40013194, 2025). "However, when rats with diet-induced obesity were treated with a ginkgo extract, the food intake and body adiposity were significantly reduced, whereas insulin sensitivity was increased, accompanied by a restored insulin-signalling cascade in muscle." (PMID 40733008, 2025). "Current evidence suggests that short-duration HIIT may be an effective alternative to conventional exercise regimens for improving insulin sensitivity and glycemic control in individuals with obesity." (PMID 40284228, 2025). "Some studies suggest that glutamine supplementation may reduce obesity and pro-inflammatory markers and improve insulin sensitivity in animal models and overweight/obese humans." (PMID 40649995, 2025). "Glycemic control and complication progression could be acceptable in HNF4A-MODY cases treated with long-time insulin, but risks of hypoglycemic events, obesity, and atherosclerosis remain." (PMID 40589512, 2025). "This difference may reflect the early stage of obesity in our model (6 weeks) or species-specific responses to metabolic stress.A critical novel observation was the coordinated upregulation of serum insulin, growth plate IR, and aromatase in obese rats." (PMID 41329658, 2025). "In Wistar male rats with HFD-induced obesity, 30-day supplementation with 6-gingerol led to lower body weight, reduced adipose tissue, and decreased levels of leptin, glucose, insulin, and serum lipid profiles compared to the control group, particularly at the dose of 75 mg/kg/day." (PMID 40733199, 2025). "Interestingly, global deletion of Nr1d1 preserves insulin sensitivity despite promoting lipogenesis, adipose tissue expansion, and obesity." (PMID 37961647, 2025). "Taken together, these studies highlight the critical role of Pak1 in regulating glucose metabolism, insulin sensitivity, and β‐cell survival, positioning Pak1 as a promising therapeutic target for T2D in addition to its promise as a target for obesity and cardiac dysfunction." (PMID 40065530, 2025). "Insulin sensitivity in adipose tissues decreases in children with obesity." (PMID 40568560, 2025). "As the relationship between automated insulin delivery systems, eating behaviour and metabolic health in people with type 1 diabetes is incompletely understood, there is a clear need for further investigations, especially in people with overweight or obesity." (PMID 39560745, 2025). "This study utilized a rhesus macaque model of SARS-CoV-2 infection to ascertain the effects of pre-existing obesity and reduced insulin sensitivity on the exacerbation of ongoing metabolic dysfunction in obese animals and/or the development of new metabolic disease in lean animals." (PMID 40027795, 2025). "Our previous studies in animal models of diet-induced obesity demonstrate that insulin drives increased airway reactivity and that selective depletion of insulin receptors on airway sensory nerves prevents both airway sensory hyperinnervation and hyperresponsiveness." (PMID 39782687, 2025). "Resistance to both insulin and leptin, resulting from PTP1B overexpression, is a characteristic condition found in complex human diseases, such as T2DM and obesity, and can also be an important risk factor for developing metabolic syndrome, cancer and neurodegenerative disorders." (PMID 41302504, 2025). "Milk protein, rich in BCAAs, can influence SI by increasing insulin levels, which may be problematic for individuals with IR, obesity, or conditions like PCOS." (PMID 40357063, 2025).
Obesity (continued). "Notably, kallikrein 7 (KLK7) has garnered attention due to its role in insulin metabolism and obesity-related phenotypes." (PMID 40427653, 2025). "In people with obesity, the antilipolytic actions of insulin in adipocytes together with an impaired lipid storage within these cells, leads to a rise in free fatty acids flux, systemic inflammation, and lipid accumulation in non-adipose tissues, triggering an increase in IR." (PMID 40195232, 2025). "In global GPRC5B-KO mice, circulating insulin levels were reduced especially in diet-induced obesity, but since KOs also showed a lean phenotype with reduced insulin resistance and lower obesity-associated inflammation, these changes might have been secondary." (PMID 40906536, 2025). "We hypothesized that TNF-α -308 G/A polymorphism influences insulin levels and HOMA-IR in adults with obesity, and that this effect may be modified by dietary antioxidant intake." (PMID 40732969, 2025). "Dysregulation of the FTO gene has been linked to various conditions, including obesity, T2D, and PCOS, through its direct effect on body weight and BMI, in addition to its impact on metabolic factors like IR, insulin sensitivity, serum glucose, and hyperandrogenemia." (PMID 40486662, 2025). "In obesity models, it reduced body weight, blood glucose, and insulin levels." (PMID 40943671, 2025). "Notably, in obesity there is a decrease in the number of immune cells that control inflammation and restore insulin sensitivity, for example eosinophils, innate lymphoid cells (ILC2) and regulatory T cells (Tregs)." (PMID 40553147, 2025). "The high expression of IER3 in macrophages may facilitate this transformation, thereby promoting the onset of obesity-related inflammation and enhancing insulin sensitivity in murine models." (PMID 40964162, 2025). "Chronic inflammation in obesity and related metabolic disorders plays a role in insulin signal transduction and may lead to insulin resistance and β-cell dysfunction, eventually predisposing to the development of long-term complications, including CVD." (PMID 41373812, 2025). "In conclusion, this study demonstrated the anti-obesity and insulin sensitivity-ameliorating effects of RFE and proposes that it is a natural product-derived material that could improve not only obesity but also its associated complications." (PMID 40076460, 2025). "This integrative strategy targets both the physiological and behavioral determinants of weight regulation, resulting in significant reductions in BMI and fat mass, as well as improvements in cardiovascular profiles, insulin sensitivity, and other obesity-related comorbidities." (PMID 40491808, 2025). "As obesity and metabolic syndrome become more prevalent in people with CF, traditional insulin-centric approaches to CFRD may be insufficient." (PMID 41439084, 2025). "We investigated whether emodin (1,3,8-trihydroxy-6-methylanthraquinone, EMO), a natural anthraquinone, mitigates RSG-induced complications while enhancing its insulin-sensitizing benefits in severe obesity." (PMID 41471299, 2025). "The disruption of this system due to obesity or sarcopenia may impair insulin sensitivity and contribute to metabolic deterioration." (PMID 40722647, 2025). "In a study of Black and White children aged 8 to 14 years among whom only 25% had obesity, hepatic insulin extraction, calculated as the incremental C‐peptide‐to‐insulin molar ratio during an intravenous glucose tolerance test, was lower in Black versus White youth." (PMID 40470991, 2025). "Female mice, even though they exhibit obesity and high insulin levels, remain normoglycemic." (PMID 40191018, 2025). "Mechanistic studies suggest these benefits may stem from curcumin’s dual ability to reduce inflammation and enhance insulin sensitivity in obesity-related conditions." (PMID 40918536, 2025).
Obesity (continued). "Clinical studies, like SURMOUNT trials, show that tirzepatide has greater anti-obesity effects than semaglutide, promoting weight and fat mass reduction, appetite suppression, energy expenditure, insulin sensitivity, and glycemic parameters in obese and diabetic patients." (PMID 41011119, 2025). "We examined how HetKO‐GAA impacts metabolic health (i.e., obesity, insulin sensitivity, glucose tolerance, fatty liver) and liver metabolism (i.e., liver glycogen content, liver glucose output, substrate metabolism, and energy expenditure) in a mouse model of HFD‐induced obesity and prediabetes." (PMID 40108792, 2025). "L-fucose, the main form of fucose found in nature, has shown promising anti-obesity effects, potentially by suppressing lipid accumulation and improving insulin sensitivity, and may be a novel strategy for treating obesity and related diseases." (PMID 40649995, 2025). "Therefore, impaired insulin clearance in obesity has been proposed as a plausible mechanism of chronic hyperinsulinemia." (PMID 40365648, 2025). "Supplementation with high-dose, long-duration purified formulations may exert beneficial effects on INS in individuals with metabolic disorders and obesity." (PMID 41586243, 2025). "Research involving American Indian adolescents and Korean children with obesity has demonstrated an inverse relationship between plasma 2-AAA levels and insulin sensitivity, with elevated 2-AAA concentrations observed in cellular and mouse models of obesity-related insulin resistance." (PMID 40432896, 2025). "In addition, the inclusion of a positive control group, such as a known anti-obesity or insulin-sensitizing agent (e.g., metformin) would allow a direct comparison of CGA’s efficacy." (PMID 40867531, 2025). "What is more, among US adults, BMI and WC could mediate the association among SUA, glucose/insulin homeostasis, and inflammation, suggesting that there are possible bidirectional associations between SUA and obesity." (PMID 40647195, 2025). "Additionally, hypothalamic inflammation and extracellular matrix (ECM) remodeling in obesity induce fibrosis around AgRP neurons, further blunting insulin signaling and promoting hyperphagia." (PMID 40452923, 2025). "Furthermore, prolactin is a lipogenic hormone, and elevated levels can result in obesity, subsequently impacting peripheral insulin sensitivity." (PMID 40362476, 2025). "We hypothesized that maternal obesity has both short- and long-term impacts on insulin sensitivity in mothers and that reducing obesity during pregnancy or after parturition may ameliorate this metabolic problem." (PMID 41463818, 2025). "These miRNAs could probably help to regulate the metabolism of fat, sensitivity to insulin, and balance of energy, which are necessary for the prevention of obesity during the growth of children." (PMID 41300824, 2025). "Furthermore, insulin resistance, which frequently accompanies obesity, exacerbates the challenge of glycemic control and weight management by increasing insulin requirements." (PMID 40707821, 2025). "Metabolic abnormalities may accelerate cartilage degeneration and subchondral bone remodeling through systemic inflammation, adipokine imbalance, insulin resistance, and oxidative stress, thereby amplifying the mechanical burden of obesity." (PMID 41459061, 2025). "However, we found a shift in the opposite direction (towards mitochondrial respiration) in PBMCs from insulin resistant children with overweight/obesity, as compared to insulin sensitive children with overweight/obesity." (PMID 40525760, 2025). "Clinical conditions of overweight and obesity are in fact characterized by release of free fatty acids and proinflammatory cytokines that eventually might contribute to reduce insulin sensitivity." (PMID 39992249, 2025). "By improving insulin sensitivity, reducing inflammation, and boosting cardiovascular health, these strategies may help manage obesity-related conditions prevalent in this demographic." (PMID 40218879, 2025).
Obesity (continued). "This may lead to a better understanding of the mechanisms linking clinical obesity to associated metabolic disease and help differentiate it from preclinical obesity, or what is known as insulin-sensitive obese individuals." (PMID 40214973, 2025). "This suggests a metabolic adaptation in obesity where stress‐related pathways compensate for impaired insulin signaling but concurrently drive sustained transcriptional reprogramming that exacerbates lipid accumulation and inflammation, fueling MASLD progression." (PMID 41024433, 2025). "Apart from obesity, insulin sensitivity is affected by multiple factors, including aging." (PMID 40568093, 2025). "Notably, interaction analyses demonstrated that older age strengthened the inverse insulin–HGS association, while higher BMI attenuated it, especially among individuals with obesity (BMI > 25 kg/m2)." (PMID 41464556, 2025). "The use of high insulin doses was also thought to have contributed to the development of obesity." (PMID 41497311, 2025). "In the first studies identifying and characterizing MHO and its underlying mechanisms in humans, it was suggested that liver fat is the predominant determinant of the insulin-sensitive phenotype of obesity, being even more relevant for insulin sensitivity than abdominal visceral fat." (PMID 40387999, 2025). "In gorillas (Gorilla gorilla), adiposity correlates with reduced foraging time and elevated insulin resistance, while over 70% of captive Asian elephants (Elephas maximus) in China exhibit obesity, primarily attributed to insufficient outdoor activity and excessive high-calorie feed provision." (PMID 40343364, 2025). "In addition, MR-proADM levels have been associated with BMI, fat mass, insulin levels, HOMA-IR, total cholesterol, and LDL cholesterol, suggesting its significant impact on obesity development." (PMID 40149642, 2025). "Given that adipocyte mitochondrial dysfunction is generally regarded as a core link in obesity-related metabolic disorders, it can damage insulin signaling through ROS accumulation, induce chronic inflammation, and thereby promote the progression of obesity and related complications." (PMID 41317904, 2025). "B. acidifaciens is known to prevent obesity and increase insulin sensitivity." (PMID 39857767, 2025). "As obesity progressed, insulin secretion (k3) increased, while insulin sensitivity (k2) decreased." (PMID 41433229, 2025). "For example, levels of hepatic miR-26a are decreased in overweight and obese humans, a change that correlates to hepatic accumulation of TG and impaired insulin signaling, suggesting that miRNA alterations could contribute to obesity-related liver disease." (PMID 41228448, 2025). "Attenuates hepatic steatosis and obesity, improves insulin sensitivity." (PMID 41393953, 2025). "Obesity is a significant driving force for adipose tissue insulin resistance (see “Obesity”)." (PMID 39998445, 2025). "The correlation between LRG1 and BMI could be explained by the relationship of LRG1 with thyroid hormones, insulin, angiogenesis, and obesity-related markers." (PMID 40665055, 2025). "Elevated ALPL levels are correlated with cardiovascular risk factors, including systolic/diastolic blood pressure, mean arterial pressure, carotid intima–media thickness, and a trend toward higher fasting insulin, a consistent and novel neutrophil activation marker in obesity." (PMID 40943443, 2025). "Likewise, in adolescents with obesity, it has been reported that fasting insulin and HOMA-IR levels are 40% higher in those with depression." (PMID 39980848, 2025). "This systematic review and meta-analysis demonstrates that interrupting prolonged sitting with brief “exercise snacks” may significantly improve glucose and insulin regulation in adults with obesity." (PMID 41356824, 2025).
Obesity (continued). "It is also possible that increased irisin levels could be a compensatory mechanism for the abnormal metabolism and insulin sensitivity characteristic of obese individuals, or who have developed a resistance to irisin suffered from obesity." (PMID 39764565, 2025). "With increasing rates of obesity it is likely that the need for higher insulin doses will increase and this may increasingly adversely affect the efficacy of slower titration schemes." (PMID 40770688, 2025). "Our analysis, therefore, demonstrates that physical training is effective in reducing the expression of senescence-related genes in SkM in middle-aged individuals with obesity, leading to improvements in insulin sensitivity, lipid metabolism, and increased activation of SkM satellite cells." (PMID 40127780, 2025). "Insulin levels were significantly correlated with MASLD in all children with obesity (p < 0.05)." (PMID 40941570, 2025). "Collectively, these studies suggest that excessive androgen secretion might contribute to metabolic dysregulation, with MAP emerging as a composite outcome of obesity, insulin metabolism, and androgen steroid activity." (PMID 41040863, 2025). "This increased insulin responsiveness in adipose tissue, due to the upregulation of lipogenic enzymes, may promote adipocyte expansion and contribute to the development of obesity." (PMID 40729034, 2025). "We demonstrate that green tea treatment in HFD‐fed mice improves insulin sensitivity, stimulates lipid metabolism pathways, and enhances glucose utilization, as previously shown in several studies using mouse models of diet‐induced obesity." (PMID 40522107, 2025). "Moreover, muscle-specific HTR2b-knockout (HTR2b MKO) mice exhibited improved glucose uptake, insulin sensitivity and overall metabolic health under high-fat-diet-induced obesity." (PMID 40451926, 2025). "However, in cases of obesity, numerous muscular metabolic pathways can be adversely altered, reducing insulin sensitivity and impairing function of insulin signaling receptors and key glucose transporters." (PMID 40522819, 2025). "Obesity induces oxidative stress, disrupting the balance between pro-oxidants and antioxidants, leading to increased fat accumulation, insulin resistance, and inflammation, particularly in visceral fat, contributing to dyslipidemia and obesity-related complications." (PMID 40149610, 2025). "Interestingly, Hdac9−/− mice were protected from diet-induced obesity and displayed improved insulin sensitivity and lower body weight." (PMID 40068774, 2025). "This dysfunction is further amplified by obesity-associated oxidative stress and chronic inflammation, which together disrupt endothelial homeostasis and exacerbate PI3K pathway impairment, ultimately blunting insulin-mediated vasorelaxation." (PMID 41439140, 2025). "Moreover, the increased prevalence of gestational diabetes among mothers with obesity further exacerbates these impairments by altering insulin signaling cascades within the mammary tissue." (PMID 40868103, 2025). "The mechanisms by which obesity contributes to neurodegeneration are diverse, involving chronic systemic inflammation, altered lipid metabolism, oxidative stress, cerebrovascular dysfunction, and impaired insulin signaling." (PMID 41155642, 2025). "Obesity also induces metabolic dysfunction, such as insulin resistance and systemic inflammation." (PMID 40589493, 2025). "In particular, hypothalamic inhibition of IKKβ has shown striking metabolic benefit in preclinical models, restoring leptin and insulin sensitivity and preventing diet-induced obesity without causing systemic immune impairment." (PMID 41463063, 2025). "In summary, the intrinsic fiber dried chicory root product resulted in higher colonic SCFA content and systemic acetate concentrations, which in turn reduced IHL content, improved blood lipid profile, and reduced adipocyte size and peripheral insulin sensitivity in individuals with obesity." (PMID 40669445, 2025).